EGF (epidermal growth factor)
Diseases named in the same sentence as EGF in open-access papers (continued):
Sharing a sentence is not in itself a finding about the gene and the disease.
Hyperglycemia (32 papers, 2010 to 2025). An increased concentration of glucose in the blood. "The much lower cell viability of the bFGF group under hyperglycemia than under normal conditions indicates a significant loss of bFGF activity in the solution under hyperglycemia, which is consistent with our previous findings with EGF." (PMID 34959393, 2021). "Hyperglycemia can cause renal tubular epithelial cells to release various cytokines, such as epidermal growth factor and transforming growth factor, which can cause renal tubular epithelial-mesenchymal transition and eventually lead to renal fibrosis (the main pathological manifestation of DN)." (PMID 41323135, 2025). "In turn, hyperglycemia causes oxidative stress and chronic inflammation, which may cause damage to DNA and the lungs, increasing susceptibility to carcinogenesis and promoting cancer proliferation through the induction of epidermal growth factor." (PMID 38902745, 2024). "Furthermore, it was shown that EGF causes a mild hyperglycaemia in mice." (PMID 28046026, 2017). "The mammalian EGFR and components of the mammalian EGF signaling pathway are known to enhance glucose absorption in the gut, induce obesity in ovariectomized and aged female mice, are decreased in adipose tissues of calorie restricted mice, and are associated with hyperglycemia in humans." (PMID 26375667, 2015). "Simultaneously, MSCs secrete various cell growth factors, such as epidermal growth factor, which reduce the apoptosis of podocytes induced by hyperglycemia and promote the repair and regeneration of podocytes." (PMID 40959421, 2025). "The composition of growth media for the enteroid culture contains the epidermal growth factor (EGF), therefore mimicking in vivo conditions where hyperglycemia and EGFR activation coexist." (PMID 37637953, 2023). "This aberrant healing response is likely attributed to a hyperglycemia-induced modulation in cell movement, since supplementation with epidermal growth factor (EGF), a potent stimulator of cell migration, was unable to restore wound closure." (PMID 37887302, 2023). "Hyperglycemia independently or jointly promotes tumor progression within the tumor microenvironment, by activating the abnormally upregulated expression of epidermal growth factor and its receptor EGFR in cancer." (PMID 35461311, 2022). "We suggest that hyperglycaemia enhances EGF signalling via EGFR–ErbB2 heterodimers, which seem to be the starting point of the pathological signalling cascade." (PMID 32548701, 2020). "In vivo reprogramming by administering long-term low-dose gastrin and EGF in hyperglycemia mouse can increase SOX9." (PMID 32118053, 2020). "When a Sox9-CreER line with stronger labelling capacity was used in a recent study, beta cell labelling was detected after mild hyperglycemia combined with cytokine (gastrin and EGF) treatment [41•]." (PMID 29227863, 2017). "Gastrin and EGF combination therapy was shown to revert hyperglycemia and increase beta cell mass in rodents." (PMID 26452142, 2015). "EGF/G treatment one day after alloxan administration, reversed hyperglycemia to normal within one day, and this persisted until the end of experiment." (PMID 26452142, 2015). "Moreover, hyperglycemia fuels the proliferation of PC cells through the induction of EGF expression and EGFR activation." (PMID 38523554, 2024). "Hyperglycemia may induce microenvironmental hypoxia, contribute to a significant increase in epidermal growth factor (EGF) transcription or secretion, activate chronic inflammation, and is associated with a higher risk of mortality in dialysis patients." (PMID 37334918, 2023). "Furthermore, EGF was shown to restore the amount of the functional β-cell mass in rats, thereby attenuating hyperglycaemia in diabetic mice." (PMID 33239104, 2020). "For example, hyperglycemia has been shown to induce collagen-I synthesis in mesangial cells by stimulating cytokines such as TGF-β and epidermal growth factor (EGF) through PI3K/Akt dependent pathway." (PMID 28386557, 2017).
Hyperglycemia (continued). "The HaCaT cells showed better viability in hyperglycemia conditions when treated with EGF-PM or EGF-Coa than the negative control or EGF solution." (PMID 32276508, 2020). "Interestingly, transient administration of epidermal growth factor (EGF) and ciliary neurotrophic factor (CNTF) to adult mice with chronic hyperglycemia efficiently stimulates the conversion of terminally differentiated acinar cells to beta cells." (PMID 29227863, 2017). "Most agents that promote inflammation activate NF-kB, including endotoxins, carcinogens, radiation, chemotherapy, hyperglycemia, tumor promoters, inflammatory cytokines [e.g., tumor necrosis factor (TNF), interleukin 1 (IL-1)], and growth factors such as epidermal growth factor (EGF)." (PMID 23805101, 2013). "However, the therapeutic efficacy compares well with a previous study of combination EGF and gastrin that also used a model of syngenic islet transplantation in diabetic NOD mice and observed that the median time to recurrence of hyperglycemia was about 8 weeks." (PMID 21966502, 2011). "Chronic treatment with AG825 or AG1478, selective inhibitors of erbB2 and EGFR respectively, did not affect hyperglycemia but led to an exacerbation whereas acute administration of the EGFR ligand, epidermal growth factor (EGF), led to an improvement in cardiac recovery in diabetic hearts." (PMID 22720029, 2012).
endometrial cancer (31 papers, 2006 to 2025). Primary or metastatic malignant neoplasm involving the endometrium (mucous membrane that lines the endometrial cavity). "This is the first study to explore the EGF gene in relation to endometrial cancer risk and survival." (PMID 19319135, 2009). "We intended to study common variation in both the ESR1 (MIM 133430) and EGF (MIM 131530) genes in relation to endometrial cancer risk, myometrial invasion and endometrial cancer survival." (PMID 19319135, 2009). "We investigated common genetic variation in the entire ESR1 and EGF genes in relation to endometrial cancer risk, myometrial invasion and endometrial cancer survival." (PMID 19319135, 2009). "Amplification of Her-2/neu, a proto-oncogene with a high degree of homology to the epidermal growth factor (EGF), is associated with local invasion and tumor progression of endometrial carcinoma." (PMID 17894888, 2007). "Using a comprehensive tagging approach of common variation in the ESR1 and EGF genes, we assessed whether common variants in the genes affected endometrial cancer risk, myometrial invasion, or endometrial cancer survival." (PMID 19319135, 2009). "In patients with endometrial cancer, increased concentrations of urinary epidermal growth factor (EGF) were measured." (PMID 38892184, 2024). "Urinary peptides and glycoproteins have been suggested as potential biomarkers for identification of endometrial cancer, among which urinary epidermal growth factor (EGF) has been found to be up-regulated in endometrial cancer patients." (PMID 36291799, 2022). "Other signaling pathways targeted in endometrial cancer include pathways like the mammalian target of rapamycin (mTOR), epidermal growth factor (EGF) and insulin-like growth factor (IGF), where receptors or kinases are targeted by specific inhibitors." (PMID 35328833, 2022). "These three pathways are EGF signaling, endometrial cancer signaling, and molecular mechanisms of cancer." (PMID 31355136, 2019). "EGF treatment of endometrial carcinoma cells was reported to induce an EGFR-dependent RIP of EpCAM, resulting in complete EpEX shedding from the membrane and in release of EpICD, which serves as a nuclear transcriptional inducer of an EMT program." (PMID 30261040, 2018). "The proliferative effects of androgen have been linked to enhancement of EGF action, increased expression of genes involved in IGF-1 and Wnt signaling or to endometrial cancer cell proliferation through activation of the oncogene c-myc." (PMID 27384477, 2016). "The suppression of EGF signaling in endometrial cancer cells with EGF inhibitor AG1478 represses EMT and cellular migration and invasion." (PMID 26356073, 2015). "MUC20 overexpression predicts poor prognosis in endometrial cancer and enhances EGF-triggered invasive behavior through activation of EGFR–STAT3 pathway." (PMID 23787019, 2013). "However, this is a study from 30 years ago, so the EGF protein and its effect on endometrial cancer requires more recent research." (PMID 37835508, 2023). "Quantification of immunoblot results did reveal an induction of EpCAM expression levels in Du145 cells treated with 1.8 and 18 nM EGF and RL95-2 endometrial carcinoma cells with 9 nM EGF for 72 hr, and a slight reduction of EpCAM expression following 1.8 and 18 nM EGF treatment of Cal33." (PMID 30261040, 2018). "Our data did not indicate that common genetic variants in the EGF gene are associated with endometrial cancer risk or myometrial invasion." (PMID 19319135, 2009). "The common variation in the EGF gene has never before been investigated with regard to endometrial cancer susceptibility, but a few studies have been published regarding ESR1 and endometrial cancer risk." (PMID 19319135, 2009). "Another potential role player in endometrial cancer aetiology is the epidermal growth factor (EGF)." (PMID 19319135, 2009).
endometrial cancer (continued). "Therefore, we can not exclude the possibility that the impairment of SRC activity can contribute directly, or has a synergistic effect with the decrease of CD44 co-receptor level, to dampen the EGF-induced or TGFβ1-induced mesenchymal marker expression in the NMU-knockdown endometrial cancer cells." (PMID 26849234, 2016). "We aimed towards capturing the entire common variation in the ESR1 and EGF genes by genotyping a dense set of markers in 92 Swedish controls and then selecting haplotype tagging SNPs (tagSNPs) that were genotyped in 713 Swedish endometrial cancer cases and 1567 Swedish controls." (PMID 19319135, 2009). "In endometrial cancer cells such as HEC265, Ishikawa, and HEC151, BPA increased cell proliferation by promoting ERRγ translocation through both epidermal growth factor (EGF)-dependent and EGF-independent pathways." (PMID 41440754, 2025). "In addition, EGF-mediated stimulation cleaves the cytoplasmic domain of EpCam (EpICD) and leads to the internalization and nuclear localization of EpCID, resulting in the transcription of genes involved in migration, adhesion, and epithelial-mesenchymal transition in endometrial cancer." (PMID 37370706, 2023). "Endometrial carcinoma cells express EGFR, and they represent a good model to investigate the role of EGF in cancer cell proliferation." (PMID 36123565, 2022). "The main cytokines secreted by CAFs isolated from human endometrial cancer tissue include MCP-1, CCL5, RANTES, interleukin-6, and -8 (IL-6, IL-8) VEGF, EGF, HGF, FGF-2, as well as TGFβ1 isoform." (PMID 34501347, 2021). "In a study examining the expression of the epidermal growth factor system in endometrial cancer, HER4 was found to be overexpressed in endometrial cancer higher than in healthy postmenopausal endometrium." (PMID 34885957, 2021). "EGF stimulation induced SOX2 expression and promoted migration of endometrial carcinoma cells, whereas TGF-β stimulation inhibited SOX2 expression and attenuated the colony-forming ability." (PMID 30510261, 2018). "Recently, Hsu and colleagues provided a link between EGF-induced EMT and RIP of EpCAM in the endometrial carcinoma cell line RL95-2." (PMID 30261040, 2018). "Lapatinib, a drug used in endometrial cancers, blocks EGFR tyrosine kinase, thereby preventing EGF signaling." (PMID 26356073, 2015). "Pathologic disruption of mRNA co-expression patterns supports the notion of a cross talk between IGF1, EGF, and FGF2 signaling pathways in the promotion of endothelial cell proliferation and differentiation of endometrial cancer." (PMID 24904527, 2014). "Epidermal growth factor (EGF) and its receptor (EGFR) constitute a principal growth-promoting pathway in endometrial cancer cells." (PMID 20579378, 2010). "Finally, the importance of PDGF-AB, PDGF-BB, TGF-α, EGF and ANG-2 in the diagnosis in endometrial cancer was evaluated." (PMID 37835508, 2023). "Our study was conducted to answer the question if PDGF-AB, PDGF-BB, TGF-α, EGF and ANG-2 could be useful as markers to diagnose patients with endometrial cancer." (PMID 37835508, 2023). "Therefore, we decided to study the preoperative serum levels of the growth factor proteins PDGF-AB, PDGF-BB, TGF-α, EGF and ANG-2 in the diagnosis of endometrial cancer." (PMID 37835508, 2023). "This study aimed to investigate whether PDGF-AB, PDGF-BB, TGF-α, EGF and ANG-2 could be considered new useful markers for diagnosis and survival of endometrial cancer." (PMID 37835508, 2023). "However, in endometrial cancer, MUC20 overexpression drives tumourigenesis, predicts poor survival, and EGF-induced malignant phenotypes were enhanced by activating the EGFR/STAT3 pathway." (PMID 36059804, 2022). "As demonstrated, molecules secreted by CAFs, i.e., TGFβ1, EGF, HGF, and FGF-2, potentiate the migration and invasion of endometrial cancer cells (RL-952) when administered exogenously, thus inducing lung metastasis in vivo in mouse subcutaneous xenograft assay." (PMID 34501347, 2021).
endometrial cancer (continued). "Moreover, EGF stimulation induced SOX2 expression and promoted migration in endometrial cancer cells." (PMID 30510261, 2018). "Treatment with a 10-fold-higher concentration of EGF (i.e., 18 nM), as compared to Hsu and colleagues, was used in order to rule out dosage effects in HNSCCs as compared to endometrial carcinoma cells." (PMID 30261040, 2018). "EGF-mediated RIP of EpCAM was reported to lead to the release of the intracellular domain of EpCAM (EpICD) that, aside from fostering proliferation, induces an EMT program in endometrial carcinoma cells." (PMID 30261040, 2018). "Insulin-like growth factor-1 and epidermal growth factor (EGF) downregulation and fibroblast growth factor-2 (FGF2) up-regulation seem to constitute key features of endometrial cancer progression, as demonstrated in a collection of 30 cancer specimens that were compared to normal adjacent tissue." (PMID 24904527, 2014). "It is well known that the p44/42 MAPK signaling pathway is activated by mitogenic stimuli from growth factors and sex steroid hormones such as estrogen, progesterone, and epidermal growth factor (EGF) in human breast, ovarian and endometrial cancer cells, among others." (PMID 23409030, 2013). "Emmprin knockdown by the siRNA led to cell proliferation, migration and invasion through TGF-β, EGF, NF-κB, VEGF, MMP-2, and MMP-9 expression, which in turn resulted in increased levels of E-cadherin and reduced levels of Vimentin and Snail in endometrial cancer." (PMID 22640183, 2012). "Overall, the inhibition caused by the emmprin siRNA affected cell proliferation, migration and invasion through TGF-β, EGF, NF-κB, VEGF, MMP-2 and MMP-9 expression, which in turn resulted in increased levels of E-cadherin and reduced levels of Vimentin and Snail in endometrial cancer." (PMID 22640183, 2012). "In the present study, RIP of EpCAM through EGF/EGFR signaling could neither be observed in an array of carcinoma cell lines nor be reproduced in RL95-2 endometrial carcinoma cells, independently of time points and EGF concentrations used." (PMID 30261040, 2018). "At present, there appear to be no updated studies on PDGF-AB, PDGF-BB, TGF-α, EGF and ANG-2 in endometrial cancer." (PMID 37835508, 2023).
liver fibrosis (29 papers, 2010 to 2025). "Stem cell factor (SCF), epidermal growth factor (EGF), and angiopoietin-2 stand among the growth factors implicated in liver fibrosis and cirrhosis, serving as indices of disease progression and prospective therapeutic targets." (PMID 39184703, 2024). "Interestingly, all these growth factors have been linked to fibrosis: PDGF-B in liver fibrosis, EGF in heart and renal fibrosis and FGF-4 in lung and renal fibrosis." (PMID 25280005, 2014). "Recently, hepatically-differentiated MSCs have been reported to ameliorate liver fibrosis through the secretion of milk-fat globule epidermal growth factor (MFGE)-827." (PMID 31048740, 2019). "Epidermal growth factor (EGF) plays a role in liver fibrosis through promoting the autocrine/paracrine proliferation and activation of HSCs." (PMID 28691020, 2017). "Although the mechanism underlying hepatic fibrosis is complex, the multi-functional transmembrane glycoprotein EGFR specifically interacts with EGF and TGF-β1, causing its dimerization and regulating cell growth, proliferation, and differentiation." (PMID 27342773, 2016). "The same applies to EGF, which plays an important role in the development of liver fibrosis and its inhibition also leads to a reduction of fibrosis." (PMID 26807786, 2016). "In the present study, CCl4 increases TIMP-1 expression so EGF expression decreases, leading to liver fibrosis due to the accumulation of collagen in the liver." (PMID 26062544, 2015). "From an overall perspective, we demonstrated that total CD4+ cells from CHB patients dramatically promoted cell proliferation, α-SMA expression and growth factors production (TGF-β, PDGF-BB, CTGF and EGF) of HSCs, thus promoting liver fibrosis progression." (PMID 22745730, 2012). "The epidermal growth factor (EGF) regulator pathway is a known contributor to hepatic fibrosis and cirrhosis, and serum EGF upregulation seemed to be associated with liver regeneration, reparation, and improved KPE outcomes in an analysis of 67 postoperative BA patients stratified for their outcome." (PMID 34062967, 2021). "While growth factors such as VEGF, EGF, and insulin-like growth factor have been shown to play important roles in liver regeneration after injury, others, such as the PDGF family and FGF, have been implicated in liver fibrosis and HCC growth." (PMID 32198380, 2020). "GA could reduce the level of EGF significantly after the animal was induced with liver fibrosis; however, whether GA is an EGFR inhibitor has yet to be determined." (PMID 30627538, 2018). "In liver fibrosis, nutrients and growth factors related to hepatocytes, such as hepatocyte growth factor (HGF)/epidermal growth factor (EGF) and insulin, can promote proliferation and repair." (PMID 36005144, 2022). "Various members of the hepatic fibrosis pathway were also differentially expressed (A2M and Col3A1 upregulated in females, and IL1R2 and EGF in males)." (PMID 23531366, 2013). "In a three-way ANOVA analysis, liver steatosis was linked with the kinetics of EGF, VEGF and ANG, while liver fibrosis was not a source of variation in our analysis." (PMID 39200991, 2024). "TCDD-induced changes in cell–cell communication patterns included marked decreases in EGF signaling from hepatocytes to non-parenchymal cells and increases in extracellular matrix-receptor interactions central to liver fibrosis." (PMID 36711947, 2023). "This is consistent with previously reported observations that other members of the EGF family including EGF, heparin-bound EGF (HB-EGF), FGF, and amphiregulin all contribute to HSC trans-differentiation and liver fibrosis." (PMID 33520984, 2020). "We found that the effects of miR-200c on HSCs and liver fibrosis are mediated via downregulation of FOG2 protein synthesis, activation of PI3K/Akt signaling, upregulation of activation of autocrine EGF signaling, and upregulation of collagen type I production in HSCs." (PMID 28691020, 2017).